BCL2 (BCL2 apoptosis regulator)
Diseases named in the same sentence as BCL2 in open-access papers (continued):
Sharing a sentence is not in itself a finding about the gene and the disease.
hepatocellular carcinoma (continued). "A-1331852 greatly potentiated regorafenib toxicity in Hep3B and HepG2 cells as measured in MTT assays after 16 h, while BCL-2 depletion with ABT-199 was not effective in increasing regorafenib action in the same hepatoma cell lines." (PMID 32024199, 2020). "Via western-blot analysis, we measured the expression levels of IP3R2 and Bcl-2 in microsomes prepared from primary hepatocytes, which have a high IP3R2 density, in human liver carcinoma HepG2 cells and in the BIRD-2-sensitive (SU-DHL-4) and BIRD-2-resistant (OCI-LY-1) DLBCL cell lines." (PMID 29899382, 2019). "In human hepatocellular carcinoma, esculetin induced apoptosis in SMMC-7721 cells by activating caspase 3 and caspase 9, promoting Bax expression, decreasing BCL-2 expression, triggering collapse of mitochondrial membrane potential, and increasing cytochrome c release from mitochondria." (PMID 31308852, 2019). "In this research, it suggests that psoralen has an exact apoptosis-inducing effect on SMMC7721 hepatoma cells, however, it is mainly not through the molecular mechanisms of the pro-apoptotic protein Bax and the apoptosis inhibitor protein Bcl-2." (PMID 31277690, 2019). "Moreover, regorafenib administration also modified the BCL-2/MCL-1 ratio and navitoclax sensitized hepatoma cells to regorafenib by a mitochondrial caspase-dependent mechanism." (PMID 29682179, 2018). "In this study, we found that rhCNB treatment resulted in a substantial decrease in expression of Bcl-2 and Bcl-xL in hepatoma cells, while no obvious reduction in normal liver cells." (PMID 29029479, 2017). "Furthermore, salinomycin induces apoptosis in hepatocellular carcinoma cells (HepG2, SMMC-7721, and BEL-7402) by decreasing the level of the anti-apoptotic protein Bcl-2 and increasing the level of the pro-apoptotic protein BAX." (PMID 25531367, 2014). "Several studies have demonstrated that primary hepatocellular carcinoma needs Omi/HtrA2 expression for cell apoptosis and HIF-1 inhibits the apoptotic process in HCC cells through upregulating Bcl-2 expression to impede Omi/HtrA2 releasing from the mitochondrion." (PMID 25101278, 2014). "Bcl-xL and Mcl-1 have been identified as major anti-apoptotic Bcl-2 proteins in the liver for previous studies revealed that Bcl-2 is not generally expressed in human hepatocytes and hepatoma cell lines." (PMID 21504623, 2011). "Additionally, apoptotic pathway analysis revealed increased expression of apoptotic markers (Cytochrome C, PARP, cleaved PARP, Caspase-3, cleaved Caspase-3, Bax) and decreased anti-apoptotic protein BCL-2 in EGR1-knockdown cells, indicating that EGR1 depletion promotes apoptosis in hepatoma cells." (PMID 41356200, 2026). "It is suggested that the combined action of 6-shogaol and curcumin against hepatocellular carcinoma may be related to the inhibition of PI3/AKT and MAPK signalling pathways, upregulation of Bax and Caspase-3 proteins, and downregulation of Bcl-2, Cyclin-B, and CDK-1 proteins." (PMID 39224778, 2024). "In hepatocellular carcinoma (HCC) cells, ketoconazole downregulates the expression of COX2, thereby triggering PINK1-Parkin-mediated mitophagy to enhance apoptosis, downregulate BCL2, BCL-XL and MCL1 and upregulate BAX and BAK." (PMID 39013891, 2024). "BCL-2 and BCL-XL were inhibited by the use of navitoclax (ABT-263) in hepatocellular carcinoma (HCC) cells, however, MCL-1 mRNA and protein were stabilized, resulting in a limited effect." (PMID 36609747, 2023). "Elevated expression of NPAS2 in hepatocellular carcinoma (HCC) triggers CDC25A transactivation, dephosphorylates Bcl-2, and ultimately inhibits apoptosis." (PMID 36978001, 2023). "Finally, sinapine thiocyanate from SS significantly decreases the protein expression of PTGS1, PTGS2, Bcl-2, MMP-2 and MMP-9 and increases the protein expression of Bax to prohibit the proliferation, migration and invasion of hepatocellular carcinoma cells in SMMC-7721." (PMID 37124205, 2023).
hepatocellular carcinoma (continued). "In addition, Alpinia oxyphylla extracts inhibited the proliferation and tumor growth in hepatocellular carcinoma (HepG2, Hep3B, Bel-7402, and SMMC-7721) cell lines and also in vivo Hep3B xenograft by increasing Bax and caspase-3/-9 expressions and decreasing Bcl-2 levels." (PMID 36500466, 2022). "In HCC (hepatocellular carcinoma) liver cancer cells, baicalein increased BAX, decreased Bcl-2, and induced cleaved caspase-3, -9, and PARP." (PMID 36142874, 2022). "Moreover, in hepatocellular carcinoma, NQO1 overexpression decreases the Bcl-2 expression." (PMID 34481509, 2021). "Publicly available ChIP-seq data in human hepatocellular cancer (HepG2) cells and mice livers suggested miR-122 could regulate BCL2 expression indirectly through c-MYC, which was confirmed by siRNA-mediated depletion of c-MYC in Hepatocellular Carcinoma (HCC) cell lines." (PMID 32650615, 2020). "In this study, we found that SAF, which was isolated from a fungal strain in our lab identified as Aspergillus aculeatus, could inhibit the progression of hepatocellular carcinoma by targeting MARCH1, which regulates the PI3K/AKT/β-catenin and antiapoptotic Mcl-1/Bcl-2 signaling cascades." (PMID 30678274, 2019). "In another study, mouse hepatoma cells treated with 30% ethanol extracts of CN in low or high doses showed a significant decrease in the expression of PCNA and p-AKT (proliferation markers) and increased expression of BAX, Bcl2, caspase-3, and PAPR (apoptosis markers)." (PMID 30806066, 2019). "Moreover, it inhibits cell growth and induces apoptosis through NF-κB suppression in Epstein–Barr virus-positive lymphoma cells, and suppresses cell proliferation and invasion through NF-κB/Bcl-2 and EGFR pathways in human hepatocellular carcinoma HepG2 and Bel-7402 cells." (PMID 31719837, 2019). "In addition, a good correlation was found between BCL-2/MCL-1 expression and sorafenib-induced cytotoxicity (0.938, Pearson coefficient) in the hepatoma cell lines examined, maybe supporting this ratio also as indicative of sorafenib efficacy." (PMID 29682179, 2018). "Furthermore, navitoclax overcame sorafenib resistance in both hepatoma cell lines, while BCL-2 inhibitor ABT-199 did not." (PMID 29682179, 2018). "Interestingly, ψ-Bufarenogin elicited a dose-dependent Mcl-1 reduction in hepatoma cells, but the levels of Bax and Bcl-2 were not remarkably altered." (PMID 25890498, 2015). "In hepatocellular carcinoma (HCC) and endometrial cancer, ADM contributes to resistance against hypoxic apoptosis and fosters cell proliferation by upregulating the anti-apoptotic protein Bcl-2." (PMID 40565016, 2025). "The developed codelivery systems inhibited the proliferation of hepatocellular carcinoma (HCC) cells, induced in HepG2 cells apoptosis and the downregulation of two target genes of the miRNA, ADAM17 and Bcl-2, as well as greater anti-tumor efficacy in vivo (BALB/c nude mice)." (PMID 38543094, 2024). "IL6R increased BCL-2 and STAT3 in hepatocellular carcinoma (HCC)." (PMID 31484561, 2019). "Furthermore, JS-K increased Bax-to-Bcl-2 ratio, released Cyt c from mitochondria and increased the activities of cleaved-caspase-9/3.Therefore, PP2A activation mechanism contributes to JS-K induced caspase-dependent apoptosis in human hepatocellular carcinoma cells." (PMID 29986744, 2018). "In addition, in this study, WCP was discovered to inhibit hepatocellular carcinoma, possibly by promoting apoptosis through the promotion of Cyto-c/Caspase8/3 and inhibition of IL-10/STAT3/Bcl2 signaling pathways, which will advance our understanding of WCP as a potential therapeutic option for HCC." (PMID 37110586, 2023).
colorectal cancer (344 papers, 1995 to 2026). A primary or metastatic malignant neoplasm that affects the colon or rectum. "For the first time, we demonstrate that the modulation of Bcl2/Bcl-xL and their associated intracellular signaling pathways plays a pivotal role in the potential anticancer activity of W. ugandensis against colorectal cancer cells." (PMID 39940328, 2025). "Recently, patients with colorectal cancer (CRC) indicates that EV-A71 is associated with immune-based anticancer therapy as EV-A71 inhibits tumor growth in nude mice CRC model by repressing Bcl-2 expression." (PMID 41210942, 2025). "One of the oncogenic causes of colorectal cancers is the overexpression of Bcl2 (B cell lymphoma 2), one of the sub-signal targets of the EGF receptor involved in the anti-apoptotic process." (PMID 38892434, 2024). "It was also observed that UA can cause colorectal cancer cell apoptosis by inhibiting constitutive NF-κB activation and downregulating cell survival proteins (such as Bcl-xL, Bcl-2), as well as metastatic proteins (such as MMP-9 and VEGF)." (PMID 39199198, 2024). "Ellagic acid sensitizes human colorectal cancer cells to 5-FU treatment through increased Bax/Bcl-2 ratio, activation of caspase-3 and loss of mitochondrial potential." (PMID 31936346, 2020). "We further validated the association between miR-139-5p and BCL2 expression levels in 66 colorectal cancer specimens and found high expression of miR-139-5p was always associated with low BCL2 expression." (PMID 27244080, 2016). "Aberrant overexpression of antiapoptotic BCL-2 (B-cell lymphoma 2) family proteins is closely linked to tumorigenesis and poor prognosis in colorectal cancer." (PMID 28035994, 2016). "We have recently shown that the pan-Bcl-2 inhibitor obatoclax blocks invasiveness of colorectal cancer cells and causes cell cycle arrest in G1-Phase." (PMID 26585594, 2015). "By targeting MCL-1 via mTOR inhibition, colorectal cancers with Kras or BRAF mutations are sensitized to BCL-2/BCL-XL inhibition." (PMID 26134786, 2015). "In addition, the potential prognostic and predictive significance of Bcl2-Associated X (Bax) and Bcl-2 gene expression as well as Bax/Bcl-2 ratio in colorectal cancer has been confirmed." (PMID 40342991, 2025). "NEIL1 inhibits apoptosis by increasing the expression of the anti-apoptotic gene, BCL2 apoptosis regulator (Bcl-2), and decreasing the expression of pro-apoptotic genes (BCL2 associated X, apoptosis regulator (Bax) and caspase-9) in colorectal cancer (CRC) cells." (PMID 40761744, 2025). "In addition, The upregulation of PVT1 resulted in elevated mRNA and protein expression levels of multidrug resistance-associated protein 1,and apoptosis regulator Bcl2, which enhanced drug resistance in colorectal cancer cells." (PMID 39830506, 2024). "However, according to a recent meta-analysis, high expression of BCL-2 is associated with a good prognosis in colorectal cancer with better overall survival and disease-free survival rates." (PMID 34066331, 2021). "A previous report has indicated that the mechanism of Rhizopus nigricans polysaccharide in the promotion of apoptosis in colorectal cancer might be associated with the regulation of the Bax/Bcl-2 signaling pathway." (PMID 32495637, 2020). "Besides, berberine was also illustrated to promoted apoptosis of colorectal cancer via regulation of the long noncoding RNA (lncRNA) cancer susceptibility candidate 2 (CASC2)/AU-Binding Factor 1 (AUF1)/B-Cell CLL/Lymphoma 2 (Bcl-2) Axis." (PMID 32328135, 2020). "Moreover, Bcl-2/Bax ratio is implicated in the response to chemotherapeutic agents in colorectal carcinoma." (PMID 27835895, 2016). "Loss of the Bcl-2 anti-apoptotic function by its phosphorylation at Serine 70 negatively correlates with tumor malignancy due to blocking of the Bcl-2 interaction with Bax, thereby resulting in favorable survival in colorectal cancer." (PMID 25826088, 2015).
colorectal cancer (continued). "In order to investigate the anticancer mechanism of emodin, reverse transcription polymerase chain reaction assays were performed to determine the B-cell lymphoma-2 (Bcl-2)/Bcl-2-associated X protein (Bax) expression ratio in LOVO colorectal cancer cells following treatment with emodin." (PMID 25187829, 2014). "In colorectal cancer, ectopic expression of miR-129 promoted apoptosis, inhibited cell proliferation and caused cell-cycle arrest by suppressing a key anti-apoptotic protein, B-cell lymphoma 2 (BCL2)." (PMID 25344911, 2014). "Bcl-2 is more expressed in colorectal carcinoma than in ordinary mucosa and associated with CRC development." (PMID 32322173, 2020). "HY0110 also exerted antiproliferative effects on HT-29 colorectal cancer cells by attenuating β-catenin and BCL-2 expression while upregulating pro-apoptotic markers P62 and c-PARP." (PMID 40238337, 2025). "In other malignancies however, BCL2 is rarely amplified and in complete contrast, BCL2 is homozygous deleted in about 5% of colorectal cancer cases." (PMID 40113751, 2025). "Unlike the defective apoptotic machinery reported in some AML and colorectal cancer subsets, all tested GC lines were effectively killed by the triple combination of BCL2, BCLXL, and MCL1 inhibitors." (PMID 40075071, 2025). "Detection of protein expressions such as Bcl2 and Bax also indicated that CaCO3@CM-OA treatment significantly activated apoptosis signals in colorectal cancer cells." (PMID 41377584, 2025). "Immunofluorescence analysis of Bcl2 showed a reduction of fluorescence intensity, indicating enhanced apoptotic signaling in colorectal cancer and pancreatic cancer cells upon CaCO3@CM-OA exposure." (PMID 41377584, 2025). "CAF-derived factors such as TGF-β and PDGF activate SMAD, PI3K/AKT and MAPK signaling, leading to upregulation of anti−apoptotic proteins (e.g., Bcl-2, Survivin) and enhanced resistance to 5-fluorouracil and oxaliplatin in colorectal cancer." (PMID 41229498, 2025). "This up-regulation subsequently leads to the inhibition of autophagy and promotes the progression of colorectal cancer, thereby firmly establishing Bcl-2 as a crucial factor in the pathogenesis of CRC." (PMID 40507857, 2025). "In colorectal cancer research, significant advancements have been made in understanding the role of Bcl-2." (PMID 40507857, 2025). "In compliance with our findings, a previous study revealed that the methanolic extract of A. absinthium increased the expression levels of BAX and caspases, where it decreased those of Bcl-2 genes in human colorectal cancer HCT-116 cells." (PMID 39770489, 2024). "The Bax/Bcl-2 ratio expression of colorectal cancer was enhanced with the statistical difference in the CTX and C + Y groups compared to the control group." (PMID 38732641, 2024). "CTSG exerts anti-tumor effects in colorectal cancer by negatively regulating the Akt/mTOR/Bcl-2 signaling pathway, and its overexpression promotes apoptosis." (PMID 39839650, 2024). "Monotropein exerts its anti-tumor effects primarily by inhibiting Bcl-2 and increasing Bax, inducing G1–S cycle arrest in colorectal cancer." (PMID 39274922, 2024). "Apigenin increased the expression of Bim and decreased the expression of Mcl-1 in the colorectal cancer cell lines HCT116, which combined with the Bcl-2 inhibitor ABT-263 to cause mitochondria-dependent cell death." (PMID 38509538, 2024). "In colorectal cancer, the apoptosis process is stopped by increasing the expression of anti-apoptotic proteins Bcl-2 and Bcl-xL due to excessive activation of NF-κB." (PMID 39409068, 2024). "The anti‐apoptotic proteins, Bcl‐2 and Survivin, are consistently overexpressed in numerous human malignancies, notably in colorectal cancer." (PMID 38494866, 2024). "The mechanism behind 2,4‐DTBP‐induced inhibition of cell proliferation and apoptosis in human colorectal cancer cells, specifically regarding Bcl‐2 and Survivin, remains to be elucidated." (PMID 38494866, 2024).
colorectal cancer (continued). "Several novel approaches to target Bcl-2 proteins and apoptotic pathways have been identified in recent years for the treatment of different types of cancer including colorectal cancer." (PMID 38173026, 2024). "A study on CDK10’s role in colorectal cancer revealed that it enhances cell growth, reduces chemosensitivity, and inhibits apoptosis by increasing the expression of BCL-2." (PMID 38609844, 2024). "Low-dose naltrexone inhibits colorectal cancer progression and promotes tumor apoptosis by increasing M1 macrophages via the Bax/Bcl-2/caspase-3/PARP pathway." (PMID 39430763, 2024). "After CAP treatment, significant changes were observed in MSI and MSS colorectal cancer cells regarding the expression of apoptosis and anti-apoptosis-related proteins, specifically Bax and Bcl-2." (PMID 38351129, 2024). "CDK10 promotes cell growth, reduces chemosensitivity, and inhibits apoptosis by increasing the expression of BCL-2 in colorectal cancer." (PMID 38609844, 2024). "Bcl2 was found to be highly expressed in colorectal cancer tissues which subsequently leads to lower apoptosis rates." (PMID 38173026, 2024). "It has been shown that Cathepsin G has a tumor-suppressive effect on colorectal cancer cells by controlling the activity of the Akt/mTOR/Bcl2-mediated anti-apoptotic signaling pathway." (PMID 39080685, 2024). "In colorectal cancer and other types of cancer, the intrinsic apoptosis pathway is often out of whack, which means that anti-apoptotic proteins like BCL2 and BCL2L1 are overexpressed." (PMID 38287097, 2024). "Overall, the integration of in silico and in vitro data suggests that 2,4‐DTBP holds promise as a therapeutic agent targeting Bcl‐2 and Survivin in colorectal cancer." (PMID 38494866, 2024). "The results showed that GF induced the apoptosis of colorectal cancer cells by increasing the expression of caspase-3, PARP, and Bax and decreasing the expression of Bcl-2 protein in colorectal cancer cells." (PMID 39314753, 2024). "We co-transfected both BCL2 TMD constructs into HCT116 human colorectal carcinoma cells and followed positive TMD interactions through the reconstitution of VFP and the associated increase in fluorescence intensity." (PMID 38670940, 2024). "Several studies on human cancer cells and mouse models have highlighted the effectiveness of co-targeting anti-apoptotic Bcl-2 proteins, as in osteosarcoma, neuroblastoma, and lung and colorectal carcinomas." (PMID 38542429, 2024). "Activation of Akt and NF-κB p65 regulated the survivin, XIAP, Bcl-xL, and Bcl-2 expression in human colorectal cancer cells." (PMID 37069612, 2023). "Recent publications demonstrated that exogenous delivery of miR-15a and, specifically, 5-FU-miR-15a significantly reduced the expression levels of YAP1 and BCL2 in pancreatic and colorectal cancer cell lines, respectively, and led to growth inhibition." (PMID 36835366, 2023). "Densitometric analysis also suggested that BAX and BCL-2 were quantitatively changed in the Δ9-THC treated colorectal cancer cells." (PMID 37837516, 2023). "AgNPs prepared from Balanites aegyptiaca aqueous extract upregulated the proapoptotic protein BIM from the Bcl-2 protein family, capable of interacting with antiapoptotic Bcl-2 proteins and the anti-inflammatory IκBα in Caco-2 colorectal cancer cells." (PMID 36836823, 2023). "This is, therefore, the first study that has successfully evaluated the downregulatory effects of A. secundiflora’s extracts on the expression of Bcl2 and Bcl-xL in colorectal cancer cell lines." (PMID 37894369, 2023). "The interaction of paxillin with Bcl-2 has been reported to be responsible for 5-FU resistance in colorectal cancer." (PMID 37175948, 2023).